IL1B (interleukin 1 beta)
Diseases named in the same sentence as IL1B in open-access papers (continued):
Sharing a sentence is not in itself a finding about the gene and the disease.
viral infection (continued). "In summary, these data indicate a highly specific response of macrophages through a coordinated negative regulation of multiple sterol pathway members upon viral infection or treatment with IFNγ or β but not IL1β, TNF, or IL6." (PMID 21408089, 2011). "The PI3 kinase inhibitor LY294002 did not inhibit the induction of either TNF or IL-1β in response to vMyxM013-KO virus infection, indicating that this pathway is not critical for induction of either cytokine in response to vMyxM013-KO virus infection." (PMID 19851467, 2009). "MiR-15a, miR-21 and miR-181a have important functions in lymphocytes development and modulations while miR-122 and miR-24 are related to virus infection and miR-146a, induced by macrophages, can activate Toll like receptor (TLR) and expose antigens to interleukin-1 beta." (PMID 19891781, 2009). "This is supported by the observation that neither expression of IL-1b nor TNFα (not shown) is significantly induced upon virus infection." (PMID 18989459, 2008). "Furthermore, analysis identified that the distribution of these immune cells correlated with the expression levels of IL1-β and HMOX1, suggesting that viral infection in the septic pathological state disrupts the balance between immune activation and suppression." (PMID 40370730, 2025). "Il1β production was unlikely triggered by direct viral infection, as neutrophils were not infected." (PMID 40127923, 2025). "The levels of IL-1β and IL-33, cytokines with important roles in metabolic homeostasis, viral infection, inflammation and carcinogenesis, are not statistically significant different in the two groups, as well as the levels of the immunoregulatory IL-10 and immunostimulatory IFN-γ." (PMID 38961336, 2024). "In fact, numerous studies on different viral infections have shown IL-1α and IL-1β to induce NSCs to favor the astrocytic lineage rather than the neuronal lineage both in vitro and in vivo either via downstream induction of the transcription factor and, at the same time, impacting on neurogenesis." (PMID 39876841, 2024). "Collectively, the earlier and our studies suggest that IFN-β may repress IL-1β production by distinct mechanisms that might depend on the biological context, e.g. if produced during the setting of a viral infection or not." (PMID 37435074, 2023). "However, we detected no further induction of IFN-α after virus infection despite a surge of pro-inflammatory responses (IL-6, IL-1β, TNF-α, IFN-γ CCL2, CCL3, and CXCL10) compared to mature hamsters." (PMID 37122119, 2023). "During bacterial and viral infections, local sensor cells in respiratory tract, including airway epithelia cells, alveolar macrophages and dendritic cells, firstly response to pathogens and secret the first-order cytokines, such as type I and III IFN, IL-6, TNF-α, IL-12, IL-25, IL-33, IL-1β, etc.." (PMID 38029253, 2023). "In addition, NLRP3 and IL-1β expression levels were significantly increased in the mouse model of herpes simplex encephalitis compared with normal mice without viral infection." (PMID 35387080, 2022). "Meanwhile, ARND also downregulated the levels of mRNA expression of proinflammatory transcription factors (NF-κB and c-Rel), proinflammatory cytokines (IL-1β, IL-6, TNF-α and CCL2) and NOS2 in vitro, which may be useful to attenuate the inflammatory response upon viral infection." (PMID 35897044, 2022). "Co-infection with a non-mucoid PA isolate increased IL-1β protein concentrations (28.88 pg/ml vs. 6.10 pg/ml), but in contrast drastically diminished levels of IL-6 protein (53.17 pg/ml vs. 2301.33 pg/ml) compared to virus infection alone." (PMID 35265536, 2022). "At the same time, the upregulation of IL1B and CXCL8, two pro-inflammatory cytokines involved in the innate immune response during the initial phases of viral infection, which could induce a good pro-inflammatory response to PVs, determining the clearance of the viral infection, was observed." (PMID 36016317, 2022).
viral infection (continued). "Indeed, the majority of IL1β, IP10, and TNFα correlates described herein comport with a large body of literature indicating the mediating roles of proinflammatory cytokines in the pathogenesis of viral infections." (PMID 34067023, 2021). "Moreover, virus infection enhanced the expressions of TNF-α, IL-1β, IL-6, IL-10, IFN-α, and IFN-β." (PMID 33827620, 2021). "Indeed, while inflammatory cytokine production was negligible (IL-1β, TNFα) or not significantly increased (IL-6), the production of IL-10 and of TNFRs was significantly enhanced upon viral infection." (PMID 34901152, 2021). "The cytokines IFN-γ, IL-1β, and TNF have a critical role in promoting inflammation and several studies demonstrated as their suppression may lead to therapeutic effects in many inflammatory diseases, including viral infections." (PMID 33544720, 2021). "Primary SARS-CoV-2 respiratory infection induces systemic inflammation (CXCL10, IFN-ɤ, IL-1B, IL-6, IL-8, IL-17, TNF-α) that can impact the musculoskeletal system through the expression of hACE2-R and TMPRSS2 genes in various types of musculoskeletal cells, allowing direct viral infection." (PMID 33919537, 2021). "IL1β thereby could strengthen the efficacy of therapeutically applied IFNα in particular in the liver and this knowledge might help to improve IFN-based strategies for the treatment of viral infections." (PMID 33002089, 2020). "Given that IFNγ, IL-1β and TNFα are upregulated by PBMC following co-culture with S. thermophilus 285 this suggests that S. thermophilus 285 induces powerful defense against invading pathogens and could be beneficial against virus infection and tumours." (PMID 32045425, 2020). "The “trained immunity” from the BCG vaccination could protect against a non-related viral infection with an attenuated yellow fever virus vaccine strain by IL-1β-mediated responses." (PMID 32570833, 2020). "Further, prior studies indicate that there is marked up-regulation of IL-1β and IL-6 in hospitalized children with serious viral infections, such as H1N1 influenza, suggesting that IL-1β may be responsible for molecular reactions that lead to airway inflammation and increased disease severity." (PMID 31766400, 2019). "Another study indicated that Mtb is able to induce the production of TNF-α and IL-1β in RAW264.7 cells and that it activates the NF-κB pathway through TLR2-mediated signaling, thereby contributing to the induction of IRF-1, one of the most potent ISGs against viral infection." (PMID 30717477, 2019). "The first barrier to viral infection is the innate immunity, which is comprised of cellular and soluble components including complement, immunoglobulin, erythrocyte and clotting factor binding (depending on species), and inflammatory cytokines (TNF-α, IL-1β, IL-6)." (PMID 30635014, 2019). "Furthermore, our previous studies indicated that IL-1β, a downstream product of NLRP3 activation, plays an important role in the protection and the pathogenesis of demyelinating disease depending on the level and time after viral infection." (PMID 28445497, 2017). "Hierarchical clustering identified a distinctive innate immune signature in bite sites that was dominated by neutrophil-attracting chemokines (CXCL1, CXCL2, CXCL3, and CXCL5) and the cytokines IL-1β and IL-6, which were not significantly induced by virus infection alone." (PMID 27332734, 2016). "IL-1β has previously been detected from primary HBEC monolayer cultures following viral infection, however we could not detect it in our models using differentiated HBEC cultures." (PMID 27583193, 2016). "Similarly, the recruitment of neutrophils to the airways and lung following viral infection was also significantly abrogated in the absence of IL-1β." (PMID 24918427, 2014). "In addition we did not detect any influence of IL-1β or the viral infection on the expression of G-CSF." (PMID 24918427, 2014).
viral infection (continued). "Instead, early stages of virus infection may activate IFN-I, which in turn leads to AIM2 expression that assists executing phases of innate immunity activation, such as processing and release of pre-synthesized IL-1β, if dsDNA is present in the cytoplasm." (PMID 21994609, 2010). "Infection of THP-1 cells with vMyxM013-KO virus significantly increased IL-1β secretion within one hour, compared to control MYXV, indicating that the vMyxM013-KO virus was uniquely unable to block the inflammasome/caspase 1-mediated response to the virus infection." (PMID 19851467, 2009). "In contrast to IFN-γ treatment, we here showed that the expression of Bgp1 drops significantly in the IL-1R1-/- liver during the viral infection, suggesting Bgp1 expression in macrophages is induced by IL-1β/IL-1R1 signaling, and lacking the pathway may compromise virus entrance and amplification." (PMID 26367131, 2015). "In the absence of viral infection, a temperature switch from 18°C to 28°C for CIK cells, or grass carp in the fish tank, significantly induced the expression of IL6, IL1β, and TNF-α." (PMID 37099596, 2023). "Virus infection resulted in induced gene expression of IFN-β, IL-1β, IL-6, and IL-8, but surprisingly not IFN-α." (PMID 32265870, 2020). "Surprisingly, IV-induced pro-inflammatory cytokines and chemokines were substantially elevated after super-infection with S. aureus, while S. aureus-induced IL-1β and CXCL8 expression levels were not escalated by viral infection." (PMID 28195157, 2017). "As a consequence, levels of pro-inflammatory cytokines and chemokines, such as IL-1β, Il-6, IL-12, CCL2 and CCL3 increased within 24 hours of CL, but not PBS treatment, prior to virus infection." (PMID 19851468, 2009). "Therefore, a strategy that reduces IL-1β, IL-6, and TNF-α levels can control allergic asthma with or without viral infections." (PMID 36501052, 2022). "We recently reported that elevated circulating markers of inflammasome activation, including IL‐1Ra but not IL‐1β predicted first‐time MI in HIV, another viral infection where inflammasome activation is probably involved in disease pathogenesis through pyroptosis." (PMID 32976665, 2021). "In time-series experiments profiling genome-wide lipid-associated gene expression of macrophages, we show a selective and coordinated negative regulation of the complete sterol pathway upon viral infection or cytokine treatment with IFNγ or β but not TNF, IL1β, or IL6." (PMID 21408089, 2011). "However, after viral infection, CINNA could reduce IL-1β levels but not significantly counteract the IL-6 one." (PMID 37986089, 2023). "We found that the level of IL-1β mRNA was not elevated in HCV (JFH-1) infected Huh7 cells, nor was the IL-1β protein being detected in SNs from these cells at day 1, day 2 or day 4 after virus infection, although the infection efficiency was found normal as indicated by HCV RNA replication." (PMID 24400125, 2014). "Furthermore, studies suggest that the reduction of IL-1β and inhibition of the NLRP3 inflammasome could impair the anti-viral immune response, exposing patients with IL-1β and NLRP3 inhibition to a more severe course of a viral infection than those without." (PMID 36905446, 2023).
Cognitive impairment (432 papers, 2012 to 2026). Abnormal cognition is characterized by deficits in thinking, reasoning, or remembering. "S1P indirectly causes cognitive impairment through mitochondrial dysfunction and increased IL-1β formation." (PMID 41325840, 2025). "Key findings indicate that elevated levels of inflammatory markers such as IL‐6, IL‐1β, and sTNFRs are linked to cognitive impairment and neurodegeneration, while the role of IL‐10 and IL‐8 present varying associations based on demographic factors." (PMID 40709483, 2025). "In 2VO rats, BOHXTN (2.5–10 g/kg, 30 days) alleviated cognitive impairment, neuron loss, decreased inflammation by inhibiting IL-1β, TNF-α, cleaved caspase-3, and iNOS by activating the PI3K/AKT and LXRα/CYP7A1 signaling pathways." (PMID 41230091, 2025). "In summary, this study demonstrates that CP induces cognitive deficits associated with increased hippocampal levels of inflammatory markers (IL-1β, IL-6, NF-κB, and TNF-α) and apoptotic markers (caspase-3 and BAX)." (PMID 41256255, 2025). "We also measured IL-1β levels as the same is associated with cognitive impairment in various diseases." (PMID 40291844, 2025). "Decreased neurotransmission is thought to be due to pro-inflammatory cytokines such as IL-1β that can lead to the catabolism of neurotransmitters and dysregulation of neurotransmission that can cause cognitive impairment." (PMID 38715789, 2024). "Inflammatory cytokines IL-1β and TNFα have been shown to be increased in AD models and around Aβ deposits and increased in patients at risk for conversion from mild cognitive impairment to AD." (PMID 38543105, 2024). "For example, in rats treated with HIV-1 gp120, IL-1β upregulation within the cortex is associated with neuronal dysfunction and cognitive deficits." (PMID 38786105, 2024). "IL-1β is important in inflammatory responses and has been implicated in both IBDs and cognitive impairment." (PMID 38891863, 2024). "Here, we show that nVNS applied before, but not after, CHI attenuates spatial memory impairment and reduces neuronal IL1-β maturation associated with cognitive deficits in this model." (PMID 38435077, 2024). "Previous studies have reported that neuroinflammation, especially increases in IL-1β, is associated with deficits in synaptic plasticity and cognitive impairments." (PMID 38596096, 2024). "More recently, when assessing different cytokines in the blood of individuals along the AD continuum, IL-1β was found to be the variable most significantly associated with mild cognitive impairment-to-dementia conversion." (PMID 36915108, 2023). "The IL-1β derived from microglia cells causes synaptic alterations associated with cognitive impairment in sepsis, resulting in synaptic elimination and inhibition." (PMID 35563317, 2022). "TNF-α and IL-6 were negatively associated with MMSE score, and high TNF-α, IL-1β, and IL-6 were correlated with cognition impairment occurrence." (PMID 35239774, 2022). "Recent studies have shown that VD can elevate ACH levels and attenuate the resulting cognitive impairment by inhibiting the expression of neuroinflammatory factors including IL-1β, BDNF, and NF-κB caused by a high-fat diet." (PMID 35754958, 2022). "As the main inflammatory cells in the CNS, microglia and astrocytes secrete several pro-inflammatory factors, such as IL-33, TNF-α, IL-1β, IL-18, IL-6, ROS, and NO, leading to neuroinflammation, which is thought to be associated with cognitive impairment." (PMID 35974336, 2022). "The ASA treatment caused a significant decrease (p < 0.0001) in the NLRP3 and IL-1β brain expression and was able to ameliorate the process of neuroinflammation and consequently the cognitive impairment induced by the administration of alcohol and/or ATOR." (PMID 35335908, 2022). "In AD mouse models, TLR and IL-1β deficiency can reduce Aβ deposition and prevent cognitive impairment." (PMID 35958583, 2022).
Cognitive impairment (continued). "Remarkably, P. gingivalis infection caused TNF-α and IL-1β expression in the brain tissues, resulting in cognitive impairment in middle-aged mice." (PMID 34831265, 2021). "After adjustment for age and sex, PD-cognitive deficit was positively associated with plasma EV pro-IL-1β, IL-6, TNF-α, and IL-10 levels and negatively with the TGF-β1 level." (PMID 33803292, 2021). "Heightened expression of pro-inflammatory cytokines, such as IL-1β, has been associated previously with mild cognitive impairment in the brains of patients with Alzheimer’s disease." (PMID 32954291, 2020). "This region of the brain is also sensitive to the insults of aging and excessive levels of IL-1β are associated with cognitive disorders in aging animal models." (PMID 30873011, 2019). "Some studies have reported that hypercapnia contributes to the risk of cognitive impairment and IL-1β secretion outside the central nervous system (CNS)." (PMID 29304864, 2018). "Our results demonstrate that TBI causes late sensorial affective/cognitive impairments linked to altered levels of cortical IL-1β, as well as phenotypic changes in the pyramidal neurons of the mPFC." (PMID 28321191, 2017). "The authors attribute this response to increased TNF-α or IL-1β production by activated microglia in the hippocampus in immature rats, which was associated with cognitive deficits and widespread neuronal loss." (PMID 28086980, 2017). "Our results reveal that after PbA-infection, the microglial production of IL-1β which affects neurogenesis and causes cognitive impairments, is mediated by IL-33/ST2 pathway, prior to the apparition of ECM-induced clinical neurological symptoms." (PMID 28448579, 2017). "It has been reported that pro-inflammatory cytokines, such as TNF-α, IL-1β, and IL-6, are associated with cognitive impairment." (PMID 28086911, 2017). "Animal model studies using LPS to mimic acute inflammation are consistent with this, showing causative roles for IL-1β and cyclooxygenase-1-mediated prostaglandins in acute cognitive deficits." (PMID 25802557, 2015). "Microglia primed by primary pathology to produce exaggerated IL-1β responses to subsequent inflammatory stimulation were implicated in the acute cognitive deficits in both of these studies." (PMID 24067500, 2013). "Furthermore, increased IL-1β was implicated in the development of cognitive deficits, especially in working memory, probably as a result of altered function of microglia and reduced BDNF production." (PMID 41010622, 2025). "Specifically, an early increase in the levels of pro-inflammatory cytokines TNF-α, IL-6 and IL-1β was generally observed across studies (measured in the hippocampus and/or plasma), with these increases being associated with the cognitive impairments observed in the animals." (PMID 41155372, 2025). "In addition, IL-1β was significantly increased and associated with cognitive impairments in both studies that measured it." (PMID 41155372, 2025). "The observed association between brain tissue volume loss and elevated levels of IL1β and T-tau suggests that these biomarkers in the blood may serve as potential biomarkers of cognitive impairment in elderly people." (PMID 39109268, 2024). "Both TNF-α and IL-1β are associated with cognitive impairment." (PMID 40017811, 2024). "Also, IL‐1β neutralization triggered a reduced hemispheric tissue loss as well as mitigated cognitive deficits following TBI in mice, signifying that IL‐1β is crucial factor in post‐injury inflammatory response." (PMID 38874089, 2024). "Additionally, several preclinical studies suggest that the blockade of IL-1β through anti-IL-1β or neutralizing antibodies attenuate inflammatory responses, brain tissue loss, and cognitive deficits following TBI in mice." (PMID 37887272, 2023). "To investigate whether inflammation is associated with cognitive impairment, we measured hippocampal expression of cytokines IL-1β, IL-6, and TNF-α." (PMID 37091543, 2023).